YKT6 (YKT6 vesicular SNARE protein)
Diseases named in the same sentence as YKT6 in open-access papers:
YKT6 is named in the same sentence as 51 diseases in open-access papers, as found by Europe PMC text mining. Sharing a sentence is not in itself a finding about the gene and the disease. The quoted sentences say what the papers report.
lung carcinoma (8 papers, 2016 to 2022). "Although this was not a prospective study, we found that a high expression level of YKT6 was associated with low survival rates in lung cancer patients with smoking experience by an analysis of the GEO database." (PMID 33800298, 2021). "We hypothesized that the expression of YKT6, the target gene of miR-584-5p, would be associated with smoking-related lung cancer." (PMID 33800298, 2021). "When the expression of another R-SNARE protein, YKT6, is decreased, the number of exosomes secreted by human lung cancer cells is also decreased." (PMID 35629824, 2022). "For example, miR-134 and miR-135b precisely regulate YKT6 expression in lung cancer cells, which in turn controls exosome release." (PMID 34193120, 2021). "In lung cancer, the suppression of YKT6 remarkably inhibited exosome secretion in the NSCLC cell line." (PMID 32499447, 2020). "YKT6 is a key molecule in the regulation of exosome release in lung cancer cells and is in turn precisely regulated by miR-134 and miR-135b." (PMID 27285987, 2016). "Here, we have shown that inhibition of YKT6 greatly affects exosome release in the lung cancer cell line A549." (PMID 27285987, 2016). "Additionally, we analyzed the overall survival rate of lung cancer patients according to the YKT6 expression level using Kaplan–Meier plots." (PMID 33800298, 2021). "In the GSE31210 dataset, YKT6 mRNA expression was significantly upregulated in tumor tissues of ever-smokers compared to the tumor tissues of never-smokers in lung cancer patients." (PMID 33800298, 2021).
breast carcinoma (5 papers, 2016 to 2026). "In breast cancer cells, YKT6 overexpression was associated with an aggressive phenotype in vitro, and with the ability of breast epithelia to metastasize when injected intravenously into mice." (PMID 27285987, 2016). "Our finding that high YKT6 expression was associated with poor prognosis is in line with previous studies in breast cancer, where YKT6 was identified as a gene that may be linked to invasive phenotypes and to tumorigenesis in breast cancer cell lines." (PMID 27285987, 2016). "Functional enrichment analysis revealed that YKT6 primarily influenced breast cancer progression through the cell cycle, as well as biological processes such as autophagy, apoptosis, and ferroptosis." (PMID 42099597, 2026). "Knockdown of YKT6 impaired the proliferation, invasion, and migration abilities of breast cancer cells, and increased apoptosis." (PMID 42099597, 2026). "The expression level of YKT6 was correlated with tumor-infiltrating immune cells in breast cancer." (PMID 42099597, 2026). "Ykt6 knockdown in human Hek293T cells caused intracellular accumulation of overexpressed Wnt3A-GFP and reduced endogenous Wnt5A secretion from SK-BR-3 breast cancer cells." (PMID 32611603, 2020). "However, the correlation between YKT6 and breast cancer remains poorly understood." (PMID 42099597, 2026).
Parkinson disease (5 papers, 2017 to 2025). A progressive degenerative disorder of the central nervous system characterized by loss of dopamine producing neurons in the substantia nigra and the presence of Lewy bodies in the substantia nigra and locus coeruleus. "Ykt6 function is disrupted by α-synuclein, a protein critically implicated in synucleinopathies such as Parkinson’s Disease." (PMID 33723042, 2021). "Lastly, previous studies have reported contributory roles for ykt6 in the onset of diseases including cancer and Parkinson’s disease." (PMID 40598917, 2025). "Phosphorylation of Ykt6 modulates its interactions in a Parkinson’s disease model, suggesting a potential involvement of this longin also in PD." (PMID 35625553, 2022). "Using a Parkinson’s disease (PD) model, we found that Ykt6 is phosphorylated at an evolutionarily conserved site which is regulated by Ca2+ signaling." (PMID 33723042, 2021). "Indeed, Parkinson’s disease α-synuclein perturbs the physiological response to lysosomal stress by impeding Ykt6." (PMID 35625553, 2022).
oral squamous cell carcinoma (4 papers, 2022 to 2025). "Specifically, regarding head and neck cancer, elevated levels of the YKT6 gene were associated with aggressive oral squamous cell carcinoma, matching what we see in our oropharyngeal cohort." (PMID 39796063, 2024). "The purpose of this study is to determine the roles of genes DKK1, HOXC6, and YKT6 in biopsy-proven oral squamous cell carcinomas and to correlate tumour severity with gene expression levels." (PMID 41477365, 2025). "YKT6, a member of the SNARE protein family, has been associated with CD8+ T cell levels and is being considered as a potential biomarker for oral squamous cell carcinoma." (PMID 38201907, 2023).
colon adenocarcinoma (3 papers, 2022 to 2025). "YKT6 expression was positively related to cancer-associated fibroblasts for TCGA tumors of colon adenocarcinoma and LGG." (PMID 37058019, 2023). "They found that YKT6 expression is significantly correlated with endothelial cells across various tumour types, including colon adenocarcinoma, HPV-positive HNSCC (HNSC-HPV+), ovarian cancer, rectal adenocarcinoma, and thyroid carcinoma." (PMID 41477365, 2025). "Furthermore, we discovered a significantly positively correlation between YKT6 expression and endothelial cell in tumors of colon adenocarcinoma, HNSC-HPV+, OV, READ and THCA." (PMID 37058019, 2023).
non-small cell lung carcinoma (3 papers, 2016 to 2021). A group of at least three distinct histological types of lung cancer, including non-small cell squamous cell carcinoma, adenocarcinoma, and large cell carcinoma. "In vitro and in vivo experiments showed that miR-584-5p suppressed migration and invasion in non-small cell lung cancer (NSCLC) cells by targeting YKT6." (PMID 33800298, 2021). "Moreover, we demonstrated that miR-584-5p is downregulated by the methylation of its promoter region and that it suppresses migration and invasion by targeting YKT6 in smoking-related non-small cell lung cancer (NSCLC) cells." (PMID 33800298, 2021).
pancreatic cancer (3 papers, 2020 to 2023). "In pancreatic cancer cells, long non-coding RNA (lncRNA) PVT-1 plays a role in MVB fusion with the plasma membrane by regulating colocalization of YKT6 and VAMP3, as well as palmitoylation of YKT6." (PMID 36674857, 2023).
synucleinopathies (3 papers, 2021 to 2025). "Moreover, we and others have implicated Ykt6 loss of function in α-synucleinopathies, neurodegenerative diseases characterized by deficits in LTP." (PMID 40840626, 2025). "This work provides a mechanistic insight into Ykt6 regulation with therapeutic implications for synucleinopathies." (PMID 33723042, 2021). "We here suggest that improving maturation and lysosomal function of cathepsins by boosting their lysosomal transport in an ykt6-dependent manner, might have a therapeutic potential to lower αSyn level in PD and other synucleinopathies (see graphical abstract)." (PMID 37312133, 2023). "Taken together, our findings highlight a critical role for Ykt6 in hippocampal function and LTP with implications for α-synucleinopathies." (PMID 40840626, 2025).
hepatocellular carcinoma (2 papers, 2016 to 2025). A malignant tumor that arises from hepatocytes. "Additionally, loss of YKT6 function can lead to impaired mitophagy and the upregulation of YKT6 is related to the progression of hepatocellular carcinoma (HCC), suggesting increased cell survival." (PMID 40025530, 2025).
Thyroid carcinoma (2 papers, 2023 to 2025). "However, the expression of YKT6 was significantly downregulated in Kidney renal clear cell carcinoma (KIRC) and Thyroid carcinoma (THCA) (P ˂ .001)." (PMID 37058019, 2023).
viral infection (2 papers, 2022 to 2025). "Additional host factors that were significantly enriched include those described for other viral infections, such as negative-stranded RNA virus vesicular stomatitis virus (VSV) (ARFRP1, SYS1, and YKT6) and the human immunodeficiency virus (HIV) (SRP14, DYRK1A, and IL2RA) (33, –, 37)." (PMID 35502904, 2022).
acute myeloid leukemia (1 paper, 2023). Acute myeloid leukemia (AML) is a group of neoplasms arising from precursor cells committed to the myeloid cell-line differentiation. "By contrast, the expression of YKT6 was low expressed in Acute Myeloid Leukemia (LAML) and THCA (P ˂ .001)." (PMID 37058019, 2023).
breast tumors (1 paper, 2016).
Cerebral ischemia (1 paper, 2022). Restriction of arterial blood supply to the brain associated with insufficient oxygenation to support the metabolic requirements of the tissue. "In this study, we found that cerebral ischemia induces neuronal autophagy, while reperfusion damages the integrity of autophagic flux, and Sec22b and Ykt6 are involved by regulating axonal autophagosome transport." (PMID 35654605, 2022).
ischemic stroke (1 paper, 2022). A stroke disorder caused by obstruction of blood flow to the brain, due to thrombotic (local blood clot formation) or embolic (due to a blood clot or other material traveling from another site) event. "Thus, Sec22b and Ykt6 play key roles in neuronal autophagic flux, and modest regulation of Sec22b and Ykt6 may help to reverse the failure of targeting autophagy induction to improve the prognosis of ischemic stroke." (PMID 35654605, 2022).
Lewy body dementia (1 paper, 2025). A progressive form of dementia characterized by the presence of protein deposits called Lewy bodies in the midbrain and cerebral cortex, and loss of cholinergic and dopaminergic neurons. "Ykt6 loss of function has been linked to α-synuclein pathology, a hallmark of Lewy body dementias, where α-synuclein misfolding in the hippocampus disrupts LTP." (PMID 40840626, 2025).
male infertility (1 paper, 2026). The inability of the male to effect fertilization of an ovum after a specified period of unprotected intercourse. "Taken together, these findings suggested that YKT6 plays an essential role in mouse spermatogenesis, whereas its ablation results in the loss of spermatogenic cells and subsequent male infertility." (PMID 40528727, 2026).
prediabetes (1 paper, 2017). "In this study, we found that a novel SNP of isolated prediabetes, rs917793 in the YKT6 gene, is related to the development of microalbuminuria." (PMID 28158221, 2017).
steatosis (1 paper, 2022). Increased lipid within the cytoplasm of cells. "In particular, the up-regulation of GTPase HRAS is associated with carcinoma, while up-regulation of Cortactin and down-regulation of YKT6 and DFFA are related to tumor cell invasiveness and down-regulation of PPIF/CypD may lead to steatosis." (PMID 36016316, 2022).
tumor (11 papers, 2016 to 2026). "The relevance between YKT6 expression, tumor-immune infiltrates and tumor mutation burden (TMB) was examined using the TCGA database." (PMID 42099597, 2026). "We also detected distinct associations exist between YKT6 and tumor mutational burden or microsatellite instability with tumors." (PMID 37058019, 2023). "Pharmacological interventions demonstrate that Wnt signaling inhibition reverses YKT6-driven malignant effects, while pathway activation restores tumor progression in YKT6-silenced cells." (PMID 41298248, 2025). "Recently, researchers have become increasingly interested in exploring how YKT6 played a role in tumor." (PMID 37058019, 2023). "We aim to investigate the gene of YKT6 across 33 different types of tumor by using the Cancer Genome Atlas, Gene Expression Omnibus database, and other several kinds of bioinformatic tools." (PMID 37058019, 2023). "TIMER2 was used to analyze the differential expression of YKT6 between tumor and normal tissues in TCGA tumors." (PMID 37058019, 2023). "Our pan-cancer analysis offers a deep comprehending the gene of YKT6 in tumoeigenesis from viewpoint of clinical tumor samples." (PMID 37058019, 2023). "We went further to analyzing the expression of YKT6 by using tumor tissues and normal tissues in TCGA and GTEx data to get detailed statistical calculations." (PMID 37058019, 2023). "The difference of YKT6 methylation between tumor tissues and matched normal tissues has distinct results at different methylation sites." (PMID 37058019, 2023). "For example, the increased expression of YKT6 is correlated with the tumor size, Edmondson Grade, metastasis, and microvascular invasion and predicts a poorer prognosis in patients with HCC." (PMID 35971121, 2022). "The analysis of YKT6 in tumor samples showed that patients with high levels had shorter disease-free and overall survival." (PMID 27285987, 2016). "RealTime-PCR analysis showed that YKT6 was expressed at lower levels in tumor than in normal tissue (p<0.0001)." (PMID 27285987, 2016). "Despite that different tumour cells may use different SNAREs to mediate exosome secretion, further investigation is needed to determine the functional importance of syntaxin‐2, syntaxin‐6, and Ykt6 in exosome secretion in different tumour cells." (PMID 37700095, 2023). "We found that “Syntaxin binding,” “SNARE complex,” “vesicle fusion” and “DNA replication” may be involved in the influence of YKT6 on tumor pathogenesis." (PMID 37058019, 2023). "Moreover, “Syntaxin binding,” “SNARE complex,” “vesicle fusion” and “DNA replication” are involved in the influence of YKT6 on tumor pathogenesis." (PMID 37058019, 2023). "Differential expression of CTTN and of YKT6 has been related to cell migration and tumor invasion." (PMID 36016316, 2022). "Although these preliminary results require further validation with a greater number of plasma samples, they provide the first indications that YKT6 levels in the tumor may act as a surrogate of exosome levels in plasma." (PMID 27285987, 2016). "In addition, we have examined the impact of YKT6 expression in tumor samples on outcome of resected NSCLC patients." (PMID 27285987, 2016). "Furthermore, we use GEPIA2 online tool to detect expression of YKT6 in different tumor stages." (PMID 37058019, 2023). "High levels of YKT6 in the tumor may lead to increased release of exosomes, leading to a more aggressive phenotype and poorer prognosis, since it is known that cancer-derived exosomes are involved in the invasive phenotype and in the formation of the premetastatic niche." (PMID 27285987, 2016). "It is demonstrated that YKT6 is significantly upregulated in BLCA tissues and cell lines, correlating with advanced tumor grade, aggressive histology, and poor patient prognosis from public datasets and tissue microarray." (PMID 41298248, 2025).
tumor (continued). "The study identified YKT6 as a promising prognostic marker and predictor of immunotherapy response in OSCC, emphasising its significance in tumour progression and immune modulation." (PMID 41477365, 2025). "This study aimed to evaluate the gene expression profiles of DKK1, HOXC6, and YKT6 in OSCC patients and explore their potential roles in tumour progression." (PMID 41477365, 2025). "YKT6, as a Soluble N-ethylmaleimide-sensitive factor attachment protein receptor (SNARE) protein with vesicle trafficking, plays an essential role in the development and progression of tumor." (PMID 37058019, 2023). "When we performed a correlation analysis between miR-134 and miR-135b expression and YKT6 expression, we could not identify a significant correlation between YKT6 and the two miRNAs in tumor tissue." (PMID 27285987, 2016).
cancer (8 papers, 2016 to 2025). A tumor composed of atypical neoplastic, often pleomorphic cells that invade other tissues. "Dysregulation of YKT6 expression or function has been associated with various pathological conditions, including cancer." (PMID 41477365, 2025). "Our study showed that YKT6 expression was positively related to cancer-associated fibroblasts for TCGA tumors of COAD and LGG." (PMID 37058019, 2023). "We detected that YKT6 level was positively associated with cancer-associated fibroblasts (CAFs) for TCGA tumors of COAD and LGG." (PMID 37058019, 2023). "In the study, we used TGCA project and GEO databases to investigate expression profiles of YKT6 across different types of cancer in a pan-cancer analysis." (PMID 37058019, 2023). "A number of factors, including gene expression, survival prognosis, genetic alteration, DNA methylation, immune infiltration, and gene enrichment analysis, were considered to explore the potential molecular mechanism by which YKT6 was involved in the pathogenesis or clinical prognosis of cancer." (PMID 37058019, 2023). "Few studies have examined the impact of YKT6 expression on outcome in cancer patients." (PMID 27285987, 2016). "YKT6 expression may be associated with the survival of cancer cells in lung and breast tissue, but how genetic polymorphisms of the YKT6 gene may exert positive or negative effects on glucose homeostasis and on related complications is still poorly understood." (PMID 28158221, 2017). "This suggested that over-expressed RNA expressions of YKT6 may be usual, but it could not reflect actual protein level or response to certain types of cancer." (PMID 37058019, 2023). "However, the gene of YKT6 has not been fully assessed in pan-cancer studies." (PMID 37058019, 2023).
YKT6 also shares sentences with these, for which no sentence is quoted: ovarian carcinoma (2 papers); rectal adenocarcinoma (2); Adrenocortical carcinoma (1); amyotrophic lateral sclerosis (1); attention deficit-hyperactivity disorder (1); bacterial infections (1); Bladder Cancer (1); Bladder Urothelial Carcinoma (1); chronic myeloid leukemia (1); Cirrhosis (1); dementia (1); diphtheria (1); endometrial cancer (1); head and neck cancer (1); head and neck squamous cell carcinoma (1); infant botulism (1); infarction (1); liver cancer (1); liver diseases (1); oral carcinoma (1); ovarian serous cystadenocarcinoma (1); pancreatic adenocarcinoma (1); primary bone cancer (1); sarcoma (1); Skin Cutaneous Melanoma (1); stomach adenocarcinoma (1); Stroke (1); testicular germ cell tumor (1); tetanus (1); uterine carcinosarcoma (1).